DNMT3A (DNA methyltransferase 3 alpha)
Diseases named in the same sentence as DNMT3A in open-access papers (continued):
Sharing a sentence is not in itself a finding about the gene and the disease.
cancer (continued). "Cancer stem cell-like cells (CSCs) displayed DNMT3a and TET2 overexpression, which were insensitive to sorafenib." (PMID 38528605, 2024). "It is well-accepted that EZH2 catalyze H3K27me3 through interacting with DNMT1, DNMT3a and DNMT3b in cancer cells." (PMID 38992588, 2024). "Given the dual function of TET2 in cancers, these findings demonstrate that a transcriptional complex of DNMT3a, TET2 and HDAC2 exists in sorafenibR HCC cells." (PMID 38528605, 2024). "DNMT3A and DNMT3B mutations cause human Mendelian disorders and somatic driver mutations are reported in cancer." (PMID 39446312, 2024). "In this study, the methylation degree revealed that as the cancer became less differentiated, DNMT3A promoter methylation decreased gradually, indicating that its expression was no longer inhibited." (PMID 38246976, 2024). "Even among various types of cancers, GBM showed the least expression of DNMT3A transcripts, despite the fact that the mutational ratio of DNMT3A in GBM was exceptionally low." (PMID 38481314, 2024). "Together, this study provides mechanistic insights into DNMT3A R882 mutations-triggered aberrant oligomerization and DNA hypomethylation in AML, with important implications in cancer therapy." (PMID 38600075, 2024). "The DNMT1 and DNMT3A or -3B family proteins are known targets for the inhibition of DNA hypermethylation in cancer cells." (PMID 38866895, 2024). "One such study has demonstrated that SFN combined with DIM significantly decreased the expression of DNMT1, DNMT3a, and DNMT3b in PC3, LnCAP, and PrEC cells, suggesting the de-methylation of the promoter region of cancer-associated genes." (PMID 36765652, 2023). "Our integrated analysis suggests that the downregulation of DNMT3A influences Sertoli cell proliferation, likely through the modulation of the Apelin signaling pathway and MicroRNAs in cancer." (PMID 38264208, 2023). "The connections between CLCN4 and the five DNA methyltransferases were assessed, DNMT3A had significantly negatively correlation in 21 cancers." (PMID 37671947, 2023). "Taken together, both DNMT3a and global DNA methylation were upregulated in chemoresistant cancer cells." (PMID 37477089, 2023). "miR-145 inhibits the expression of DNMT3A by directly binding to the 3’-UTR of its mRNA, and circIQCH downregulates miR-145 by function as its sponge, so as to relieve its negative regulation of DNMT3A and promote cancer progression." (PMID 37901333, 2023). "It has been well‐known that DNMTs, including DNMT3a, were upregulated in many disorders, such as cancers." (PMID 37477089, 2023). "The FCM results exhibited the inhibitory effects of miR-26a-5p on cancer stem cell-like properties, and the opposite effects of DNMT3A for miR-26a-5p." (PMID 35860691, 2022). "Aberrant methylation patterns are often associated with frequent mutations in genes that regulate DNA methylation (such as DNMT3a and TET2) in human cancers, leading to abnormal gene expression in human cancers." (PMID 35140720, 2022). "RT-qPCR and Western blot tested the downregulated miR-34a-5p and PTEN, and upregulated c-MYC and DNMT3a in cancer tissues and cells." (PMID 34623601, 2022).
cancer (continued). "We have previously shown that p2x3r DNA demethylation is most likely due to a reduction in DNMT3a/b under diabetic and cancer pain conditions." (PMID 34890016, 2022). "Note that DNA methyltransferase 3A—DNMT3A is a de novo methyltransferase involved in establishing DNA methylation patterns in development and cancer." (PMID 36499286, 2022). "DNMT3A and 3B levels were increased significantly in cancer cell secretion groups, in agreement with the elevated methylation in DNA." (PMID 35265687, 2022). "Among the 15 canonical genes associated with CH, our cancer patients had mutations in CHEK2, DNMT3A, ASXL1, PPM1D, and TET2 only." (PMID 35428225, 2022). "CpGs associated with DNMT3A mutations, which tend to be hypomethylated, are more likely to reside in regions associated with gene expression (CGI shores), cancer (C-DMR), and cellular reprogramming (R-DMR)." (PMID 36097025, 2022). "Our study found that RMI2 is related to DNA methylation in multiple types of cancer, among which BRCA, STAD, UCEC is associated with four DNA methylation genes (DNMT3L, DNMT3B, DNMT3A, DNMT1)." (PMID 35552266, 2022). "MLL4 expression is positively correlated with levels of DNMT1 and DNMT3A in most TCGA human cancer types and across human cancer cell lines." (PMID 36323669, 2022). "miR-145-5p has been found to suppress cancer cell proliferation, invasion, stemness, chemotherapy, and radiation sensitivity in patients with PCa by targeting different regulators such as DNMT3a, TWIST1, ITPR2, AR, and NMT3b." (PMID 35368699, 2022). "Further investigation confirmed DNA hypomethylation and upregulation of SEMA3A tumor suppressor gene, promoter of which was shown to be bound by DNMT3A in cancer cells in our previous studies." (PMID 36296971, 2022). "In a data set from TCGA, we see that DNMT3B is the main de Novo methyltransferase overexpressed in epithelial carcinomas (6/6) with respect to DNMT3A (2/6)." (PMID 36460706, 2022). "Other mutated cancer genes included those involved in Wnt signaling (APC, AMER1), mitogen signaling (KRAS, BRAF), epigenetic modification (ARID1A, ARID2, DNMT3A, NCOA3) and DNA repair (RAD50, BRIP1, ERCC5, RECQL4)." (PMID 33776923, 2021). "Horizontal analysis indicated that TET2, DNMT3B, DNMT3A, and DNMT1 demonstrated much higher mutation frequency among 33 cancers." (PMID 34325709, 2021). "Meanwhile, genes regulating DNA methylation, including DNMT1 and DNMT3A, the TET family and IDH1 and IDH2, are themselves frequently mutated in cancer and their mutation status is associated with changes to the cancer epigenome." (PMID 34871444, 2021). "Although three genes, DNMT3A, ASXL1 and TET2, are hot genes, CH mutations also appear in other genes, particularly some driver genes that are indicators for cancer therapy." (PMID 34658138, 2021). "Resveratrol treatment has inhibited DNA methyltransferases (DNMTs) including DNMT1, DNMT3a, and DNMT3b expression and activity in human cancer cells." (PMID 34633989, 2021). "The DNMT3A, TET2 and ASXL1 genes had the most mutation sites in different cancer types from the Chinese populations." (PMID 34658138, 2021). "UCEC exhibited a significantly higher number of mutations across pan-cancers, analogously TET2, DNMT3B, DNMT3A, and DNMT1 have placed a moderate burden in m5C regulator genes." (PMID 34325709, 2021). "Significant inhibition was achieved in cancer cells and animals bearing tumors that harbor deleterious TET2 and nonsynonymous DNMT3A mutations." (PMID 34039392, 2021). "DNMT1 is responsible for maintaining global methylation and aberrant CGI methylation in human cancer cells, whereas DNMT3a and DNMT3b are believed to act as maintenance and de novo methyltransferases." (PMID 33959155, 2021).
cancer (continued). "Lachance and colleagues demonstrated that the proliferation of cancer cells in a hypoxic microenvironment is driven by activation of the HIF2α pathway; resulting from naturally occurring defects in DNMT3a." (PMID 33088284, 2020). "Several reports have demonstrated that DNMT3a and DNMT3b are fre-quently overexpressed in cancers with poor prognosis, and targets of the miR-29 family, miR-101, miR-143, mir-148a and miR-152 have been reported in various forms of cancer." (PMID 33050637, 2020). "On the disease connections, we used a NSD2 gain-of-function model which led to the discovery of potential therapeutic implication of DNA inhibitors in the related cancers, while the other study only used NSD1 and DNMT3A loss-of-function models." (PMID 31814083, 2020). "DNMT3a, as a crucial regulator of methylation, mediates the epigenetic silencing of TSGs and contributes to cancer progression." (PMID 33365310, 2020). "In particular, DNMT3a has been reported to be degraded by the ubiquitin proteasome system in cancer cells." (PMID 33177984, 2020). "Although several studies showed the direct link between DNMT3A and miR-29b in other human cancers, little studies showed the direct correlation between miR-429 and DNMT3A in any type of human cancers." (PMID 32597790, 2020). "In fact, by three different approaches, the co-expression score of UHRF1 and DNMT1 is higher than that of DNMT1 and DNMT3A, which was previously proposed to be coordinately co-expressed in order to maintain DNA methylation homeostasis in cancer cells." (PMID 30696879, 2019). "Our pan-cancer analyses revealed that mutations in epigenetic modifiers, namely SETD2 and DNMT3A, are major determinants of ITH." (PMID 30897760, 2019). "We have analyzed the DNMT3A expression among the different cancer types using the information of the recent clinical studies included in The Cancer Genome Atlas (TCGA) and CBioPortal database." (PMID 31861499, 2019). "A pronounced increase in histone H3 methylation on Lys 923 or Lys 2724 is a prerequisite step for de novo methylation at the promoter by the enzymes DNMT3A/3B in early embryonic or cancer genes." (PMID 31110221, 2019). "Strikingly, cancer cell migration increased as a result of DNMT3A-3 L targeting, but decreased by TET1 targeting or overexpression of WNT5B complementary DNA (cDNA)." (PMID 29871649, 2018). "Apart from the upregulation of TET2 and TET3, we also found that there is a significant downregulation of both DNMT3a and DNMT3b expression in cancer tissue compared with normal tissues." (PMID 29983831, 2018). "There was significant overlap; 8/14 genes involved in OGID were somatically mutated in a diverse range of cancers (NSD1, EZH2, DNMT3A, PTEN, CHD8, HIST1H1E, MTOR, PIK3CA; p = 1.7 × 10−14)." (PMID 28475857, 2017). "As a crucial regulator of methylation, DNMT3A mediates the epigenetic silencing of tumor suppressor genes and then contributes to the progression of cancer." (PMID 28743276, 2017). "Extension to this analysis to other cancer-types such as brain, lung, ovarian, and bladder also reinforced the notion that high MTA1 and low DNMT3a combination associates with an overall poor patient survival." (PMID 28393842, 2017). "Despite a recognized role of DNA methyltransferase 3a (DNMT3a) in human cancer, the nature of its upstream regulator(s) and relationship with the master chromatin remodeling factor MTA1, continues to be poorly understood." (PMID 28393842, 2017). "On the other hand, the levels of DNMTs, especially DNMT3a and DNMT3b, are often increased in various cancer tissues and cell lines such as HCT 116 cells." (PMID 28090275, 2017). "Next, we examined the status of MTA1 and DNMT3a in 877 cases from the Cancer Cell Line Encyclopedia using cBioPortal database." (PMID 28393842, 2017). "Because of the significant clinical implications of the noted inverse MTA1-DNMT3a relationship, we next investigated the mechanism of MTA1 regulation of DNMT3a expression in cancer cells." (PMID 28393842, 2017).
cancer (continued). "We compared mRNA levels of DNMT1, DNMT3A, total DNMT3B, and DNMT3B variants in cancer tissue with those in matched adjacent normal tissue." (PMID 28160561, 2017). "To explore the nature of relationship between the status of MTA1 and DNMT3a in human cancer, we first interrogated the available breast and colon microarray public datasets for the levels of DNMT3a and MTA1." (PMID 28393842, 2017). "Interacting genes included well-established cancer-connected genes such as DNMT3A, SMAD2, MTCP1 and TLE4 (refs 36, 37, 38, 39)." (PMID 28534499, 2017). "Once again, we found a remarkable reverse relationship between MTA1 upregulation and DNMT3a downregulation in most cancer types with a low degree of exception to this relationship." (PMID 28393842, 2017). "In our analysis, we found that epigenetic proteins DNMT3A, HDAC2, KDM6A, and TET2 are highly mutated in variety of cancers." (PMID 26777304, 2016). "Analysis of this data shows that some epigenetic proteins such as DNMT3A, HDAC2, KDM6A, TET2 are highly mutated in most of the cancer cell lines." (PMID 26777304, 2016). "We present evidence that UHRF1/2 overexpression is likely a common mechanism for suppressing DNMT3A activity and consequently widespread DNA hypomethylation in cancers." (PMID 27462454, 2016). "We confirmed overexpression of DNMT3A in six out of eight cancer types and DNMT3B overexpression in all cancer types, compared with normal tissues." (PMID 27121154, 2016). "Consistent with previous publications, these RNA-seq data indicate that both DNMT1 and DNMT3A are also frequently overexpressed in these cancers." (PMID 27462454, 2016). "Altered DNA methylation is a common hallmark of cancer, and 200, 590, and 320 somatic mutations in DNMT1, DNMT3A, and DNMT3B, respectively, have been reported in the catalog of somatic mutations in cancers (COSMIC)." (PMID 25815005, 2015). "For the target specific methylation, SKOV3 cancer cells, which have an unmethylated EpCAM promoter and active EpCAM expression, were transiently transfected with the chimeric Zinc finger - Dnmt3a catalytic domain (ZF-Dnmt3aCD) constructs." (PMID 24489952, 2014). "DNMT1 controls precise duplication and maintains the pre-existing global DNA methylation patterns after duplication in addition to gene-specific methylation in human cancer cells and DNMT3a/b are involved in de novo methylation." (PMID 25340937, 2014). "DNMT3A functions in de novo methylation, is important in development and altered expression levels have been found in several different types of human cancers." (PMID 25134718, 2014). "As we previously discussed, several epigenetic modifiers such as EZH2, IDH1/2, and DNMT3A are genetically altered in cancer." (PMID 23533770, 2013). "In summary, our results uncover conserved features of cancer methylomes and define the role of Dnmt3a in maintaining DNA methylation patterns in cancer." (PMID 23284304, 2012). "The aberrant CpG methylation patterns in human cancer cells are inscribed by the de novo DNA cytosine-5 methyltransferases (DNMTs), DNMT3a and DNMT3b, and transmitted in the subsequent cell generations by the maintenance DNMT1." (PMID 21629434, 2010). "DNA Methyltransferases (DNMT1, DNMT3a/3b) contribute to aberrant methylation patterns in cancer." (PMID 40650308, 2025). "This occurs through the downregulation of DNA methyltransferases DNMT1, DNMT3A, and DNMT3B, and the upregulation of Methyl CpG Binding Domain Protein 2 (MBD2), a marker often associated with cancer due to its role in causing genomic instability and increasing mutation frequencies." (PMID 39829957, 2025).
cancer (continued). "Zinc deficiency increased the expression and activity of DNMT1 and DNMT3A in human cancer cell lines and upregulated DNMT1 and downregulated DNMT3A in the hippocampus of cognitive dysfunction murine models, wherein these DNMT alterations were significantly mitigated by zinc supplementation." (PMID 39941940, 2025). "Treatment strategies centered around DNMT3A, such as the application of DNMT3A inhibitors, may well constitute a novel direction for future cancer therapy." (PMID 40675967, 2025). "Alterations in DNMT3A levels are associated with chronic diseases and cancers in cigarette smokers and non-smokers." (PMID 40003580, 2025). "In summary, by elucidating a novel functional link between YAP/TAZ and DNMT3A‐mediated DNA methylation during cancer metastasis, we identified a previously unknown interaction between DNMT3A and YAP/TAZ." (PMID 38380551, 2024). "Finally, we performed sequencing for epigenetic regulators, for example, DNMT3a and TET2 that are frequently mutated in cancers, in sorafenibR Hep3b and Huh7 cells." (PMID 38528605, 2024). "Additionally, our study, in alignment with prior studies, demonstrates DNMT3A and TET2 to be the common genes to be mutated among cancer cohorts." (PMID 39456832, 2024). "It will likely prove important in determining how DNA methylation changes occur in cancer, where the role of DNMT3A and DNMT3B remain unclear despite reported mis-regulation, altered splicing and mutations." (PMID 39446312, 2024). "DNMT3A is a key gene in the methionine metabolism and predicts a poor cancer prognosis." (PMID 38246976, 2024). "Mutations in DNMT3A and DNMT3B cause rare Mendelian diseases in humans and are cancer drivers." (PMID 39446312, 2024). "This hypothesis was supported by recent publications, reporting that DNA methylation at MKX and other homeobox genes was detected in solid tumors via a pan-cancer screen, and that OCI-AML3 carries a pediatric AML-associated mutation in DNMT3A." (PMID 39689089, 2024). "We have previously reported that mTORC2 is a critical driver of metabolic as well as epigenetic reprogramming in cancer cells, and we thus hypothesized that the expression of DNMT3A might be epigenetically regulated by mTORC2." (PMID 38481314, 2024). "To further establish the relevance of these findings to human biology, we measured DNMT3A levels in circulating HSPCs from the blood of cancer-free, healthy younger and older donors and of patients with NSCLC, from whom we documented increasing frequencies of HSPCs with age and worsening stage." (PMID 39236155, 2024). "We then attempted to identify any potential associations between these PVs/LPVs (DNMT3A and ASXL1 excluded) and the clinical characteristics of MBC patients, namely, the presence of a first- or second-degree relative with cancer, personal history of cancer, BMI and smoking." (PMID 37762649, 2023). "The perturbations of DNA methyltransferase 3 alpha (DNMT3A) may cause uncontrolled gene expression, resulting in cancers and tumors." (PMID 37628829, 2023). "Thus, the regulation mechanism of DNMT3A expression is quite complicated in different types of cancer cells and needs to be clarified especially in childhood B-ALL." (PMID 36934225, 2023). "AntiGan treatment increases DNMT3a immunoreactivity; this is mostly localized to the cytoplasm, suggesting that this treatment may slow cancer progression." (PMID 35054489, 2022). "Once cancer-associated mutations in CEBPA, it relieved DNMT3A inhibition and promoted AML." (PMID 36091786, 2022). "In the present study, we found miR-26a-5p exerted antitumor effects on NSCLC by inhibiting cancer stem-cell like properties through downregulating the DNMT3A to increase SFRP1 expression and then increasing SFRP1 inhibited Wnt/β-catenin pathway in the regulatory process." (PMID 35860691, 2022). "In addition, a close relationship was observed between PLOD2 expression and mutations in 4 methyltransferases (DNMT1, DNMT2, DNMT3A, DNMT3B) in several cancer types." (PMID 35586565, 2022).